CD4 (CD4 molecule)
Diseases named in the same sentence as CD4 in open-access papers (continued):
Sharing a sentence is not in itself a finding about the gene and the disease.
infection (continued). "Furthermore, studies in HIV-infected individuals at different stages of infection revealed that CTLA-4 also is selectively upregulated on HIV-specific CD4+ T cells in all categories of HIV-infected subjects besides long-term non-progressors (LTNPs)." (PMID 23514593, 2013). "Furthermore, in contrast to CD4+ T cells specific to antigens expressed solely during lytic infection, both the UL138 and LUNA-specific CD4+ T cell responses included CD4+ T cells that secreted the immunosuppressive cytokine cIL-10." (PMID 24130479, 2013). "It has been demonstrated previously that during L. major infections high local Arginase-1 levels at the site of infection mediate L-arginine depletion, which results in impaired local CD4+ (and CD8+) T cell function, particularly IFN-γ production but also to a lesser extent IL-4 and IL-10." (PMID 23437409, 2013). "Thus, clear parallels exist between the dominance of CCR5-dependent strains of HIV-1 and CD134 CRD2-dependent strains of FIV during early infection, culminating in the efficient targeting of a specific CD4+ helper T cell population." (PMID 23992667, 2013). "However, in mice immunized subcutaneously with peptide/CFA, or infected intravenously with C. muridarum, an expanded population of CD44hi CD4 T cells was detectable 7 days post immunization or infection." (PMID 24204262, 2013). "More in general, enhancing the recruitment of CD4+ T cells during natural infection or immunization with potential vaccines could result in a longer lasting protective effect of memory." (PMID 23580062, 2013). "In addition to the study of CD4+ responses in pregnant women and young children with post-natally acquired infections, the CD4+ responses of the CMV-infected fetus has been evaluated in several studies." (PMID 24023565, 2013). "The up-regulation of CD134 on feline CD4+ T cells following activation [4••,5•], and the high levels of surface expression achieved [8•], are consistent with the selective targeting of these cells in early infection." (PMID 23992667, 2013). "However, significant differences between C57BL/6 and IL-22−/− mice were only seen at d43 and d219 of infection with reduced numbers of naive CD4+ T cells and increased amounts of central memory T cells in mutant mice, respectively." (PMID 23460846, 2013). "Additionally, HIV replication in CD4+ cells requires that cells express an activated phenotype and intercurrent infections that induce immune activation have been found to increase HIV disease progression." (PMID 23327493, 2013). "Moreover, our data on the presence of CD4+CD25+Foxp3+ Treg cells at the site of infection are in good agreement with ours, and others reports showing a late enhancement of Foxp3+ Treg cells associated with increased immunological responses and pathogen burden." (PMID 23936574, 2013). "Furthermore, severe cases resulting from infection with JaOArS982 exhibited a significant reduction of CD4+ and CD8+ doubly-positive cells in the thymus." (PMID 23940775, 2013). "Although the selective targeting of FIV to helper T cells may be explained by the restricted expression pattern of CD134, in early infection, the primary cellular targets for the virus are not only CD4+ helper T cells, but also monocytes." (PMID 23992667, 2013). "We regard the transient low CD4 counts as an outcome rather than cause of infection, as the counts increased when the systematic infection was treated." (PMID 23514617, 2013). "Thus, supplementing IFN-α early after LCMV-WE infection significantly improved early (day 2) and late (day 12) viral control and restored CD4+ and CD8+ early life T cell responses." (PMID 24376875, 2013). "Impaired lamina propria Foxp3+ Treg-cell responses were associated with increased production of IL-4 and IL-13 by CD4+ T cells, demonstrating that ICOS dominantly downregulates Type 2 responses at the infection site, sharply contrasting with its Type 2-promoting effects within lymphoid tissue." (PMID 23319295, 2013).
infection (continued). "Moreover, CD4+ T cell depletion upon primary infection with HIV-1 has been reported to occur in the gastrointestinal tract." (PMID 23885255, 2013). "Similarly, the in vitro modulation of the expression of CCR5 and RANTES in CD4+ T lymphocytes by statins, as well as their inhibition of infection by R5 strains of HIV-1, was previously demonstrated." (PMID 23634877, 2013). "NP-2/CD4 cells were completely resistant to infection by all HIV and SIV strains tested." (PMID 24009735, 2013). "A possible explanation to reconcile all these observations may be that LTNP have reduced CCR5 expression on a critical CD4 effector subset, especially during PHI, making them less susceptible to infection and loss." (PMID 23630526, 2013). "As such, elevated levels of Tregs in HESN may protect against infection by limiting activation of conventional CD4+ T cells." (PMID 24257114, 2013). "Besides their mandatory role in inducing humoral immunity, CD4 T cells also produce cytokines, which control infection and regulate responses to limit pathology, and they seem to be required for the optimization and maintenance of CD8 T cell memory." (PMID 23383106, 2013). "Multiparameter flow cytometry has revealed extensive phenotypic and functional heterogeneity of CD4 T cell responses in mice and humans, emphasizing the importance of assessing multiple aspects of the immune response in correlation with infection or vaccination outcome." (PMID 23383106, 2013). "Finally, Model III explores the possibility of enhancing efficacy of the treatment by co-transfecting stem cells with A3G and a gene circuit that induces activation of the apoptosis pathway in progeny CD4+ T cells upon infection by HIV." (PMID 23724012, 2013). "However, anti-IL-12p40 treatment reduced migration of CD4+ T cells towards infection-derived liver cells, primarily by abrogating the hepatotropic migratory capacity of T cells, rather than diminishing soluble tissue-derived migratory signals." (PMID 24244314, 2013). "Thus, DCs and monocytes/macrophages account for a first wave of IL-10 production, followed by a second wave of IL-10 production by DCs, CD4+ T cells and monocytes/macrophages on day 5 post infection." (PMID 24244162, 2013). "Moreover, an infection of memory CD4+ T cells that revert back to a resting state ensues as well, resulting in a dormant stage of the virus that is undetectable by the host’s immune system." (PMID 23705941, 2013). "How CD4+ T cells become activated, how they differentiate into effector cells, how effector phenotype of CD4+ T cells is maintained, and whether T cell effector phenotype can be changed to better control infections has been a subject of intensive research." (PMID 23966946, 2013). "This may arise from cells that are productively infected with HIV and revert to a resting memory T-cell phenotype with integrated pro-virus (post-activation latency) or via direct infection of resting CD4+ T cells (pre-activation latency)." (PMID 23846220, 2013). "In contrast, achieving diagnosis before 8 years post-infection minimizes mortality rates to stable levels, maximizes life expectancy and allows prevention of early mortality through initiation of treatment at higher CD4 counts." (PMID 23308161, 2013). "This infection preferentially targets antigen-responding CD4+ T cells." (PMID 24278768, 2013). "Dissemination and formation of the reservoir is believed to be fueled by inflammation and infection of responding activated CD4 T-cells, and it has been proposed that some of these activated cells revert to long-lived resting memory T-cells containing replication competent provirus." (PMID 23630526, 2013). "Efficient infection of resting CD4+ T cells in close contact with mDC and HIV could explain the rapid early establishment of the latent HIV reservoir." (PMID 24339779, 2013). "We previously reported a devastating impact of LAI infection on CD4+ CD8+ thymocytes." (PMID 24172637, 2013).
infection (continued). "However, adoptive transfer to nude mice of CD4+ or CD8+ T cells derived from normal mice previously infected with C. muridarum resolved the infection." (PMID 23457650, 2013). "Furthermore, animal models show that control of the infection and clearance of L. pneumophila depend on recruitment and function of CD4+ and CD8+ T-cells." (PMID 23646123, 2013). "Importantly, infection of CD11c+ DC-T cell cocultures with R5 virus resulted in productive, trans infection of CD4+ T cells, whereas cis infection of these DC with HIV-1 was inefficient." (PMID 24278768, 2013). "We observed a substantial increase in IL-10 expression by CD4+ T cells following infection." (PMID 23555256, 2013). "However, bacterial dissemination also coincided with elevated systemic Chlamydia-specific CD4 T cell responses and resolution of primary infection." (PMID 24204262, 2013). "Interestingly, in vivo administration of Tc Muc during murine experimental infection with Trypanosoma cruzi parasites rendered lower frequencies of splenic IFN-γ producing CD4+ T cells in the host compared to infected controls." (PMID 24204874, 2013). "The interaction of major histocompatibility complex (MHC) class II molecules on the surface of the antigen-presenting cells (APCs) and CD4-positive T lymphocytes plays a central role in regulating the cell-mediated immune response against infection with the Cryptococcus species." (PMID 24058271, 2013). "Of particular interest is that the development of long-lived CD4 T cell mediated Th2 effector responses are induced at specific tissue sites of infection by the migrating parasite leading to subsequent Th2 mediated effector responses that can confer local immunity at that tissue site." (PMID 23518620, 2013). "Consequently, DC scavenge for HIV-1 in peripheral tissue before moving on to lymphoid tissue, where HIV-1 gains access to CD4+ T lymphocytes, the main targets of infection." (PMID 23590845, 2013). "Several similarities between HIV-1 and pathogenic SIV (Simian Immunodeficiency virus) infection of macaques exist including chronic immune activation, mucosal immune dysfunction, microbial translocation and high levels of infection of central memory CD4+ T cells." (PMID 23803414, 2013). "These animals displayed widespread infection of tissue macrophages, which express very low levels of CD4 compared to CD4+ T cells, indicating a mechanism by which virus could expand its target cell range in this setting of limited CD4+ T cell targets." (PMID 24219995, 2013). "Therefore, in the presence of productive infection it is possible that there are alternative pathways that lead to the establishment and maintenance of latency in resting CD4+ T cells." (PMID 24339779, 2013). "Interestingly, when CD4+Foxp3− conventional T cells were examined for IL-35, negligible levels were found in the spleen, whereas CD4+Foxp3− T cells at the infection site had a significant increase in IL-35 expression." (PMID 24151492, 2013). "Our model of persistent infection studying the role of aging and memory indicates recruitment of CD4+ T cells to the site of infection as a fundamental process to target in order to affect a significant change in the long term dynamics of persistent infections." (PMID 23580062, 2013). "Thus, SP-D appears to be a dual modulator of HIV infection by protecting CD4+ T-cells from direct infection but enhancing the transfer of HIV from DCs to CD4+ T-cells." (PMID 23527085, 2013). "These patients could have developed infection at lower CD4 counts prior to ART initiation and remained antigenemic as their CD4 count improved on ART." (PMID 23469276, 2013). "Moreover, pDC activation following Cpn infection enhanced CD4 Tregs/IL-10 production and mediated the regulation of T cell responses for optimal immunity against infection." (PMID 24386207, 2013).
infection (continued). "Considering NHP models, a simple question must be asked –WHY do these viruses, albeit “cytolytic” after in vitro stimulation, not cause in their hosts a very rapid depletion of CD4 T lymphocytes, in all models of infection?" (PMID 24321528, 2013). "However, following infection the IL-10 came from both CD4+Foxp3− and CD4+ Foxp3+ T cells, and about 50% of the CD4+Foxp3− T cells producing IL-10 also produced IFN-γ." (PMID 23555256, 2013). "The next logical step was to determine whether PAMP-treated human DCs (i.e. mDCs) can effectively be directly infected by X4 virus, a process that can lead to a subsequent cis-infection of CD4+ T cells." (PMID 23844079, 2013). "Taken together, recent work suggests that the phenotype of pathogen-specific effector CD4+ T cells may change over the course of infection due to cellular plasticity of T helper subsets." (PMID 23966946, 2013). "Only a few CD4+ T cells could be sorted from semen, but these cells transmitted the infection when cocultured in vitro with a permissive cell line, demonstrating their considerable capacity to produce infectious SIV." (PMID 24348253, 2013). "In several animal infection models, helminth parasites such as H. polygyrus, Litomosomoides sigmodontis or Schistosoma mansoni, induce regulatory responses via different regulatory cells, most prominently the CD4+CD25+Foxp3+ population." (PMID 23844022, 2013). "In these self-healing mouse models, and possibly subclinical human infections, CD4+ T cells can extend their effector functions beyond the immunological synapse and activate bystander effector activities, including CXCL10and iNOS, to control intracellular pathogens." (PMID 23801993, 2013). "The skewed distribution of the resting CD4+ T cells observed in the PTCs is also found in uncontrolled early infection (our own unpublished results), further indicating that early therapeutic intervention strongly contributed to the nature of the viral reservoir in these individuals." (PMID 23516360, 2013). "However, the total number of CD4+CXCR3−GFP− cells remained unchanged, further indicating that infection promotes the recruitment of CD4+CXCR3+ T cells." (PMID 24130498, 2013). "In Brucella infection it has been proposed that CD4+ T cells display a cytotoxic potential upon Brucella vaccination and it has been shown that perforin -/- mice have a decreased ability to control B. abortus replication at early stages of infection." (PMID 24367519, 2013). "Similarly, infection of humanized mice transplanted with CD4+ T-cells expressing the mC46 fusion inhibitor peptide resulted in the positive selection of genetically modified CD4+ T-cells following HIV-challenge." (PMID 24287598, 2013). "It is unlikely that there are technical explanations for these results as the treatments prevented the chemotaxis of infection-derived CD4+ T cells towards the relative recombinant chemokines, and pertussis toxin treatment inhibited chemotaxis towards all tested chemokines." (PMID 24244314, 2013). "In addition, macrophages are known to express both CCR5 and CXCR4; early investigations by using HIV-1 isolates showed HIV-1 is being adapted to use CXCR4 in addition to CCR5 expressed by both macrophages and CD4+ T cells along with infection progression." (PMID 23741458, 2013). "CD4+ αβ T cells strongly increase their ability to produce IFN-γ after infection with P. berghei." (PMID 24009610, 2013). "Consequently, 50% or more of HIV+ persons present to care late in the course of their infection and with CD4 counts below 350 cells/μl." (PMID 23767777, 2013). "Some NK cells express CD4 and are susceptible to HIV-1 cis infection." (PMID 24278768, 2013). "If the viremia is driven primarily by the de novo infection of active CD4+ T cells, it represents an ongoing source of viral mutants that could eventually result in mutational escape from antiviral therapy." (PMID 23658114, 2013).
infection (continued). "Moreover, we assessed the functional role and localization of infection-induced CD4+Foxp3+ regulatory T cells (Treg) in mediating such suppressive effects." (PMID 23967364, 2013). "We have quantified the latent reservoir in peripheral CD4+ T-cells during asymptomatic phase of FIV-C infection to be approximately one in 105 cells (1 in 103 cells is infected, but only 1:100 of those is replication competent), with just one provirus per infected cell." (PMID 23829177, 2013). "To avoid abortive infection, in our experiments, we used soluble gp120 and purified CD4 T cells; this allowed us to observe the unusual effects of Env-dependent Akt activation, and how we might exploit these pathways in new therapies." (PMID 23742646, 2013). "The infection frequency of naïve CD4+ T-cells isolated from peripheral blood of patient 5 ranged from 1600–1846 cells/HIV-1 DNA molecule, similar to the overall frequency of infection of naïve CD4+ T-cells in lymph node tissue (2376–2857 cells/HIV-1 DNA molecule)." (PMID 23818847, 2013). "At various time points after infection, higher number of CD4+ and CD8+ T cells were recruited to the lungs and MLN of WT mice compared to TLR4−/− mice, with significant differences observed from days 3 to 8 p.i. in the lungs and days 5 to 8 p.i. in the MLN compartment." (PMID 24205331, 2013). "Dendritic cells may act as catalysts for the infection of CD4 T cells via cell-cell transfer, but activated CCR5+ CD4 T cells are the main target for infection and the main source of viral replication throughout the acute phase." (PMID 24455433, 2013). "CD4+ T cells are the main target of infection and play a pivotal role in regulating immunity to HTLV and are hypothesized to participate in the pathogenesis of HAM/TSP." (PMID 23409198, 2013). "We next hypothesised that increased CD4+ T cell accumulation within livers of WSX-1−/− mice after day 10 of infection was due to active CD4+ T cell migration, most probably from the spleen, which is the major site of T cell priming during malaria infection." (PMID 24244314, 2013). "In multivariate analysis, there was no clear effect on the rate of loss of TDR mutations of CD4 cell count (P = .5) or viral load (P = .2) at the first resistance test, recent infection (P = .3), or the number of mutations detected at the first test (P = 1.0)." (PMID 23904291, 2013). "Hence, IFN-γ produced by vaccine-primed CD4+ T cells was required for mediating adaptive immunity against infections." (PMID 24324681, 2013). "Since HIV preferentially replicates in activated CD4+ T cells, immune quiescence may protect against infection by limiting HIV target cell availability." (PMID 24257114, 2013). "Moreover, PAMP-treated DCs (particularly those exposed to bacterial- and yeast-derived products) have the capacity to sensitize CD4+ T cells for a productive infection with HIV-1." (PMID 23844079, 2013). "For example, for CD4, all cats had an increase during the first week after infection." (PMID 23409138, 2013). "We show that IL-27 both inhibits the migratory capacity of infection-derived CD4+ T cells towards infection-derived liver cells, but also suppresses the production of soluble liver-derived mediator(s) that direct CD4+ T cell movement towards the inflamed tissue." (PMID 24244314, 2013). "Therefore, the partial reduction of CD4+ T cells in blood seen with LAINeffs∆-1 and LAINeffs∆-13 infection is systemic." (PMID 24172637, 2013). "In summary, we have shown that CD11b+ cells exposed to pre-patent schistosome infection are impaired in their ability to stimulate CD4+ T cells and that this may contribute to an overall reduction of T cell responsiveness during pre-patent infection." (PMID 23556020, 2013). "This early mortality could be explained by the advanced stage of infection and the low CD4 cell count of patients at enrollment, due to late presentation of patients." (PMID 23339377, 2013).